LYN (LYN proto-oncogene, Src family tyrosine kinase)
Diseases named in the same sentence as LYN in open-access papers (continued):
Sharing a sentence is not in itself a finding about the gene and the disease.
tumor (continued). "High expression of both cytoplasmic LYN and cytoplasmic S1P3 or nuclear phosphorylated c-RAF-1 and nuclear S1P3 in the same tumor is associated with shorter disease-specific survival time." (PMID 23316473, 2012). "The known blood cell oncogene LYN is located in this interval and it is up-regulated in several of our tumor samples." (PMID 16982006, 2006). "Our study establishes a Tumor Microenvironment-derived Prognostic Model (MPM) that integrates eight TME-associated genes (CXCL12, GZMB, ITPR2, LYN, RAB9B, RGMB, RUFY4, TRIM16) to stratify AML patients into distinct risk categories with significant survival differences." (PMID 40608798, 2025). "Thus, for MC inhibition in the context of IgE‐dependent allergic or KIT‐driven neoplastic diseases, co‐inhibition of LYN, FYN, and KIT would be an evident advantage." (PMID 39676406, 2025). "Thus, the efficacy of LYN inhibition in CLL is to some extent based on an emerging new function of LYN in regulating the tumor microenvironment and the dialog between leukemic cells and bystander cells." (PMID 38469232, 2024). "LYN staining of these varied significantly with tumour genotype (Kruskal–Wallis test, P=0.0063)." (PMID 38149669, 2024). "Lyn-high/PCA group 3/4 tumours had a higher histoscore than Lyn-low/PCA group 1/2 tumours, so we next assessed whether there was an association between LYN staining of tumour cells, as assessed by histoscores, and B-cell abundance." (PMID 38149669, 2024). "However, several studies suggest an emerging new role of LYN as a crucial regulator within the CLL tumor microenvironment supporting leukemic cell growth and CLL progression." (PMID 38469232, 2024). "This has the advantage of ensuring that sensitive RNA expression patterns are not altered during cell purification protocols but, assuming that Lyn expression in Lyn-high tumours was a result of both LYN-expressing tumour cells and immune cells, interpretation of the results is complex." (PMID 38149669, 2024). "As LYNKO in stromal cells particularly affected cytokine- and ECM-related pathways and resulted in a reduced tumor support, we postulate that LYN expression in stromal cells may modulate CAF features." (PMID 36899005, 2023). "Next, we evaluated the effects of LYN knockdown on Brca1 tumor cell growth." (PMID 30590041, 2018). "Overexpression of LYN could promote cell migration and invasion, but inhibit cell death in vitro, and also promote tumor formation in vivo via activating NF-κB signaling pathway which could be reversed by miR-218-5p." (PMID 30524205, 2018). "Therefore, while both LYN isoforms promoted tumor cell growth, only LYNA drove aggressive behavior in these cells." (PMID 30590041, 2018). "Thus, clinical prognostic outcome is linked with the combined high expression of nuclear SK1 and cytoplasmic phosphorylated c-RAF-1 or cytoplasmic phosphorylated AKT or nuclear ERK-1/2 expression or cytoplasmic Y416 phosphorylated SFK or LYN in the same tumor." (PMID 23316473, 2012). "In addition, high expression of both nuclear S1P3 and nuclear SK1 or cytoplasmic LYN and cytoplasmic S1P3 in the same tumor is associated with shorter recurrence time." (PMID 23316473, 2012). "However, it is possible that LYN-dependent signalling pathways in tumour cells activated intrinsic inflammatory signalling pathways, potentially including NFκB, resulting in the production of cytokines that enhanced immune cell recruitment and an anti-tumour immune response." (PMID 38149669, 2024). "In addition, LYN promoted tumor formation in vivo, but miR-218-5p reversed the effects of LYN." (PMID 30524205, 2018). "Our results indicated that LYN may play an important role in the tumor metastasis process." (PMID 27690342, 2016). "Furthermore, LYN has been recently shown to act as a mediator of tumor invasion." (PMID 22523595, 2012).
tumor (continued). "MIR31 deletion upregulated LYN, enhancing stiffness perception and promoting O-GlcNAc addition to NICD1, finally resulting in mechanoadaptation- and tumor stemness-driven recurrence." (PMID 41632535, 2026). "Oncogenes show specific activity in tumor cells, with LMO2, LYN, TNFRSF17, CARD11, and BCL7A being active in Tumor B1, while BCL2 and WAS are specifically active in Tumor B2." (PMID 41238550, 2025). "For example, Src family kinases HCK, FRK and LYN are onco-homologs of PDGFRA/KIT, which interact with both PDGFRA and KIT as downstream effectors and play critical roles in tumor cell proliferation and survival." (PMID 29844492, 2018). "In particular, downregulation of LYN and/or FYN, that we find overexpressed in primary NSCLC tumours as compared to normal lung, impairs the growth of NSCLC cells." (PMID 29937990, 2018). "Co-immunoprecipitation (coIP) demonstrated that in mouse Brca1 null tumor cells, PIN1 interacted with LYN." (PMID 30590041, 2018). "Two additional genes (CD14 and CSNK2A1) were dysregulated in MSS tumours and two genes (CARD11 and VCAM1) were downregulated and six genes were upregulated (LYN, TICAM2, ICAM1, IL1B, CCL4 and PTGS2) in MSI tumours." (PMID 29188362, 2018). "Numerous oncogenes and tumor suppressors are directly regulated by PIN1, and here we show that PIN1 is an important contributor to LYN hyperactivation in BRCA1 mutant tumor cells." (PMID 30590041, 2018). "Our data show that in normal mammary epithelial cells, LYN kinase activity is under the strict control of the c-KIT receptor, whereas in Brca1 mutant tumor cells, LYN functions independently of c-KIT." (PMID 30590041, 2018). "The observation that LYN and FYN are widely overexpressed NSCLC tumours while being undetectable in normal lung tissue is consistent with the previously suspected involvement of these SFKs in transformation and tumourigenesis." (PMID 29937990, 2018). "FAK signaling has been shown to regulate proteins (e.g. SRC, SYK, FYN, LYN, GRB2, PI3K, and paxillin) that are involved in modulating cytoskeleton rearrangements to enhance tumor growth and metastasis." (PMID 27472394, 2016). "We also found that high LYN expression in samples had positive correlation with FIGO stage and tumor grade." (PMID 27690342, 2016). "SRC, LYN and CKB immunoreactivity was detected in 72 (52.2%), 66 (47.8%) and 0 (0%) of the tumor samples." (PMID 26460485, 2015). "The co-expression network suggests that by influencing the interplay of CD86 and neural signal features such as LYN, PLXNC1, and DOCK10, it may mediate the interaction between neural signals and M1 macrophages, thereby affecting anti-tumor activity." (PMID 41147013, 2025). "LYN staining in Lynfl/wt tumours was reduced compared to that in Lynwt/wt tumours but the difference was not statistically significant." (PMID 38149669, 2024). "It was the B-cell infiltrate that correlated with the doubling time of the tumours rather than levels of LYN expression in the tumour cells." (PMID 38149669, 2024). "Moreover, MCM8 knockdown inhibited tumor growth, RPS15A expression, and phosphorylation of P38α, LYN, and p70S6K in vivo." (PMID 38988047, 2024). "There were, however, outliers showing that in some tumours, there was not a direct correlation between Lyn expression by RNAseq and LYN staining by IHC." (PMID 38149669, 2024). "Moreover, LYN, MMP2, PRKCQ, and TLR1 can affect SKCM by influencing tumor cell metastasis, UV-induced cell injury, the NF-κB signaling pathway, and apoptosis." (PMID 36171883, 2022). "Besides, based on the tumor anatomic structure of GBM, LYN expression was more enriched in hyperplastic blood vessels." (PMID 35186945, 2021). "SRC, LYN and CKB proteins or DNA methylation could serve as markers for predicting tumor progression and target in anti-cancer strategies." (PMID 26460485, 2015).
tumor (continued). "Additionally, proteins involved in the regulation of the cell cycle (e.g., ATM and STAT3), cell proliferation (e.g., LYN and SRRT), metabolism (e.g., GOT2, PPP1CA, and PYGB), and the regulation of Ca2+ flux (e.g., ANXA6 and CALM1) were also found phosphorylated in the tumor cells." (PMID 40129242, 2025). "Therefore, to directly assess LYN expression levels in tumours from the three cohorts, 13 Lynwt/wt tumours, 21 Lynfl/wt tumours and 20 Lynfl/fl tumours – all adenocarcinomas (no special type) – were randomly selected for staining for LYN protein." (PMID 38149669, 2024). "This suggested that genotype could not be fully relied upon to predict LYN expression in any one individual tumour." (PMID 38149669, 2024). "However, some Lynfl/fl tumours clearly retained strong LYN staining, whereas some Lynwt/wt tumours showed very little or no staining." (PMID 38149669, 2024). "Based on our integrative multi-omics analysis, we argue that LYN in fibroblasts orchestrates in general inflammatory signaling events and in particular the CAF-like polarization of stromal cells, inducing widespread changes in gene signatures, marker expressions and tumor-promoting functions." (PMID 36899005, 2023). "Given the role of many SFKs in immune signaling pathways, increased phosphorylation of SFKs, such as LCK, LYN, FYN, and FGR could be associated with immune cell activation, rather than tumor cell signaling." (PMID 36077757, 2022). "Total LYN knockdown led to a decrease in cell growth, but this could be rescued by either LYNA∗ or LYNB∗, indicating that these two distinct LYN isoforms can compensate for each other in promoting tumor cell growth." (PMID 30590041, 2018). "However, dasatinib treatment did not inhibit tumor growth in xenografts of H23 cells, which had undetectable LYN expression." (PMID 27756880, 2016). "Therefore, SRC, LYN and CKB expression or DNA methylation could be useful markers for predicting tumor progression and targeting in anti-cancer strategies." (PMID 26460485, 2015). "Furthermore, partially methylated LYN in non-neoplastic samples was also more frequently detected in individuals presenting tumor samples with partial methylation of this gene compared with tumors with hypermethylation (p = 0.004)." (PMID 26460485, 2015). "SRC and LYN partial methylation in non-neoplastic samples was more frequently observed in individuals presenting tumor samples with hypomethylation of this gene compared with tumors with partial methylation (p < 0.001, for both analyses) or hypermethylation (p < 0.001, for both analyses)." (PMID 26460485, 2015).
cancer (48 papers, 2007 to 2025). A tumor composed of atypical neoplastic, often pleomorphic cells that invade other tissues. "Multi-omics profiling reveals that LYN regulates the polarization of fibroblasts towards an inflammatory cancer-associated phenotype through modulation of cytokine secretion and extracellular matrix composition." (PMID 36899005, 2023). "Of all of the other family members (FYN, YES, BLK, YRK, FGR, HCK, LCK, and LYN) cSrc is the most often associated with cancer progression." (PMID 33841333, 2021). "These histamine receptors interact with proteins, such as HNMT and LYN, suggesting a complex regulatory mechanism involving histamine signaling in cancer progression." (PMID 39267843, 2024). "Like most genes regulating growth traits, LYN plays an essential role in the occurrence and development of cancers since it can function in the signal transduction of growth factor receptors." (PMID 37237371, 2023). "Activation of LYN is also known to participle in promoting the EMT process in various types of cancers 46,47." (PMID 37416766, 2023). "We further revealed that LYN expression was a hazardous marker in eleven cancer types and a favorable marker in seven cancer types." (PMID 35186945, 2021). "LYN inhibition increases cancer cell apoptosis, and reduces cancer cell proliferation, migration, and invasion, likely by inactivating the WNT/Beta-Catenin and AKT/mTOR pathways and activating the mitochondrial apoptotic pathway." (PMID 33233470, 2020). "This was also true for SRC and LYN, although less patient samples were tested due to limited availability of cancer tissue." (PMID 32082487, 2020). "In particular, SRC together with YES, FYN and LYN were often found co-overexpressed in our cancer cell lines and tissue sections." (PMID 29937990, 2018). "While the overexpression/hyperactivation of SRC is associated with poor prognosis in patients suffering from various cancers, similar studies for LYN and FYN led to varied conclusions." (PMID 29937990, 2018). "Using a drug-immunoaffinitychromatography approach, LYN was identified as one of the 18 tyrosine kinase targets of dasatinib in a lung mucoepidermoid cancer cell line." (PMID 27756880, 2016). "The increased LYN expression was significantly correlated with cancer differentiation and FIGO stage." (PMID 27690342, 2016). "LYN (located at 8q13) is among the highly ranked signature genes overexpressed in EnD versus EnA carcinomas and documents a strong correlation between DNA and RNA analysis." (PMID 22040021, 2011). "Hence, developing novel inhibitors of LYN is urgently required and will hold great promise for the therapy of advanced cancer." (PMID 35414768, 2022). "LYN has been reported to be overexpressed in various cancers, including CRC 10-13." (PMID 35414768, 2022). "In addition to regulating cell death, FYN and LYN participate to cancer cell invasion and metastasis." (PMID 29937990, 2018). "Also, the impact of LYN and FYN on NSCLC patients’ survival may be linked to their ability to regulate biological process associated with cancer progression, such as resistance to apoptosis and metastasis." (PMID 29937990, 2018). "However, LYN overexpression has been reported in several cancers." (PMID 26460485, 2015). "Through direct binding, minocycline inhibits the kinase activity of LYN, leading to reduced STAT3 activation, thereby represses the EMT and metastasis of cancer cells." (PMID 35414768, 2022). "Our data show that minocycline directly binds and inhibits LYN activity, leading to inhibition of EMT and metastasis of cancer cells by suppressing STAT3 signaling." (PMID 35414768, 2022). "Cenisertib inhibits the kinase activity of AKT as well as FLT3, VEGFR2, LYN, BTK, and KIT and promotes growth inhibition, cell cycle arrest, and apoptosis in many cancer cell lines." (PMID 36590916, 2022). "The phosphorylation levels of p-LYN and p-STAT3 were found to be inhibited following minocycline treatment in these listed cancer cells." (PMID 35414768, 2022).
cancer (continued). "Considering the top drugs able to modulate the predicted candidate genes, both Dasatinib and Ilorasertib share the same target genes (LYN, CSF1R, FYN) and are used as anti-cancer drugs." (PMID 33918694, 2021). "For instance, in the current sample, the genes GNAS, GNAQ, and GNA11 were widely altered across cancer types, and these alterations often were accompanied by specific genomic abnormalities in AURKA, CBL, and LYN." (PMID 34150649, 2021). "These 8 genes (SPP1, TTK, MELK, FOXM1, LYN, ARRB2, COL6A3, and CCL21) were further validated in more numbers of cancer tissue samples by quantitative real-time PCR (qRT-PCR)." (PMID 33829064, 2021). "LYN is a member of the SRC family of protein tyrosine kinases (SFKs), which are key regulators of several cellular processes, including cancer cell growth, migration, invasion, and survival." (PMID 34490085, 2021). "The interactive analysis tool was applied to confirm the expression level of the eight DEGs (SPP1, TTK, MELK, FOXM1, LYN, ARRB2, COL6A3, and CCL21) in cancer and normal tissues." (PMID 33829064, 2021). "For instance, G-Rh2 induces the apoptosis of cancer cells by inhibiting FGFR2, CSF1R, EGFR, and LYN." (PMID 33488754, 2020). "In Class I we identified mammalian onco-homologs assuming oncogenic functions with onco-signatures always intact in cancer, such as HCK and LYN." (PMID 29844492, 2018). "For another, the correlations between miR-218/LYN/NF-B signaling pathway axis and HPV infection or pre-neoplastic lesions or with cancer progression were needed to further investigated in this study." (PMID 30524205, 2018). "LYN is a member of SRC family of protein tyrosine kinases, and is the key regulators of several cellular processes as well, including cancer cell growth, migration, invasion, and survival." (PMID 27690342, 2016). "This threshold was met in at least one cancer cell line by 39 (52%) kinases and by 23 kinases in at least two cell lines, including CDK5, CSK, LYN, RSK2 and YES." (PMID 22277058, 2012). "Furthermore, these transcription factors are enriched in cancer-related kinases such as lymphocyte-specific protein tyrosine kinase (LCK), LYN proto-oncogene (LYN), spleen tyrosine kinase (SYK), Janus kinase 3 (JAK3), and FER tyrosine kinase (FER)." (PMID 40612864, 2025). "Functional validation of our nanodrug in cancer cell lines suggests that the Src member LYN plays a pivotal role in mediating the resistance to DASA no matter in naïve or in nanoparticle system." (PMID 38739359, 2024). "LYN is one of nine SFK family members, which participate in signal transduction and regulate various processes, including growth, survival, migration, and invasion, in cancer cells." (PMID 27756880, 2016). "The fact that LUX has activity at or upstream of LYN is important because LYN is an essential signaling intermediate in multiple cellular signaling processes that regulate growth, differentiation, apoptosis, immunoregulation, migration and EMT in normal and cancer cells." (PMID 36888611, 2023). "Meanwhile, there is evidence that Lyn regulation of VAV1 in cancers activates the Rac1-PAK1 kinase cascade to stabilize Slug and Snail, allowing them to initiate transcription of EMT genes 14, so the metastasis-related tyrosine protein kinase LYN attracted our attention." (PMID 35414768, 2022). "However, to date LYN inhibitors have not been clinically used for cancer management." (PMID 35414768, 2022).
infection (7 papers, 2009 to 2023). The state of being infected such as from the introduction of a foreign agent such as serum, vaccine, antigenic substance or organism. "Besides these three kinases, network enrichment analysis highlighted the general importance of kinases in infection development, e.g. JAK1, LYN, TYK2 and PRKCZ." (PMID 36579860, 2023).
inflammation (3 papers, 2020 to 2023). Aberrant reaction of the microcirculation characterized by movement of fluid and leukocytes from the blood into extravascular tissues. "LYN downregulates allergen-induced airway inflammation, and its overexpression decreases mucus secretion and MUC5AC transcription in mice exposed to allergens." (PMID 35886039, 2022). "Some literatures show that LYN in allergic airway inflammation can reduce inflammatory cell infiltration and levels of IL-13 and IL-4 and downregulate allergen-induced airway inflammation." (PMID 33215029, 2020).
adenocarcinoma (2 papers, 2016 to 2024). A common cancer characterized by the presence of malignant glandular cells. "LYN expression was associated with poor overall survival in a multivariate analysis, and this association was strongest in non-smoker female patients with adenocarcinoma (ADC)." (PMID 27756880, 2016). "Most importantly, our study suggests that non-smoker female patients with adenocarcinoma and high LYN expression (27 of 151 ADC cases, 18%) may show PRs to dasatinib therapy, and that this treatment may improve clinical outcomes in these patients." (PMID 27756880, 2016).
cardiovascular disease (1 paper, 2019). "Interestingly it is known that LCK, LYN, and FYN are part of the SRC-family kinases (SFKs) and have been associated with various aspects of cardiovascular disease." (PMID 30717456, 2019).